YBEY (ybeY metalloendoribonuclease)
Description:
Single strand-specific metallo-endoribonuclease involved in rRNA maturation.
Synonyms: C21orf57
Tractability: PROTAC: ubiquitination databases record sites on it; its protein half-life has been measured.
Gene: Protein-coding gene on chromosome 21 (46,286,336 to 46,297,811, forward strand). Ensembl gene ENSG00000182362.
Subcellular location: Nucleus
Subcellular location (Human Protein Atlas): Nucleoplasm
Gene Ontology:
Molecular function: protein binding; RNA endonuclease activity; metalloendopeptidase activity
Biological process: rRNA processing
Cellular component: mitochondrion; nucleus
Genetic constraint (gnomAD): Loss-of-function variants: 13 observed, 12.24 expected, observed/expected ratio (o/e) 1.06, 90% interval 0.69 to 1.66. The upper end of that interval is the gene's LOEUF score, 1.66, which puts it in group 6 of 6, group 1 being the genes least tolerant of losing a copy. Missense variants: 220 observed, 190.49 expected, observed/expected ratio (o/e) 1.15, 90% interval 1.03 to 1.29. Synonymous variants: 93 observed, 72.33 expected, observed/expected ratio (o/e) 1.29, 90% interval 1.09 to 1.53.
Homologues: Orthologues: chimpanzee YBEY (99% identical), macaque YBEY (81% identical), guinea pig YBEY (78% identical), rat Ybey (78% identical), mouse Ybey (76% identical), rabbit YBEY (75% identical), pig YBEY (71% identical), dog YBEY (58% identical), zebrafish YBEY (57% identical), tropical clawed frog ybey (52% identical), Caenorhabditis elegans swsn-9 (13% identical), Drosophila melanogaster Brd7-9 (11% identical). Paralogues in human: BRD7 (25% identical), BRD9 (22% identical).
Diseases named in the same sentence as YBEY in open-access papers:
YBEY is named in the same sentence as 11 diseases in open-access papers, as found by Europe PMC text mining. Sharing a sentence is not in itself a finding about the gene and the disease. The quoted sentences say what the papers report.
breast carcinoma (3 papers, 2020 to 2022). "Our study investigated YBEY, an uncharacterized gene in humans, and its functions in breast cancer risk and progression." (PMID 33922500, 2021). "A prior exome sequencing study conducted in a Chinese population identified rs13047478 to be associated with breast cancer risk, and subsequent eQTL analysis indicated that this variant was associated with YBEY expression." (PMID 33922500, 2021). "Our results show, for the first time, that several genetic variants may play a role in breast cancer risk through modulation of human YBEY expression." (PMID 33922500, 2021). "Overall, our study has provided preliminary evidence that the human YBEY gene, and SNPs associated with its expression, may have a potential causal function in breast cancer risk." (PMID 33922500, 2021). "Our previous GWAS and subsequent eQTL analysis suggest that YBEY expression may be inversely associated with breast cancer risk." (PMID 33922500, 2021). "We identified two genetic variants associated with YBEY expression that may have causal functions in breast cancer risk." (PMID 33922500, 2021). "Our study provides evidence of a significant role for the human YBEY gene in breast cancer pathogenesis and the association between the rs35418111/21q22.3 locus and breast cancer risk, which may be mediated through functional SNPs, rs35418111 and rs2078203, that regulate expression of YBEY." (PMID 33922500, 2021). "We investigated the biological effects of YBEY on breast cancer cell lines by transient knock-down of YBEY expression in MCF-7, T47D, and MDA-MB-231 cell lines." (PMID 33922500, 2021). "In our study, we explored the biological relevance of the YBEY gene in human breast cancer cell lines using in vitro functional assays to assess proliferation, colony formation, and invasion/migration." (PMID 33922500, 2021). "We showed that cellular functions, including proliferation, colony formation, and invasion/migration, were significantly reduced following YBEY mRNA k.d. in human breast cancer cell lines." (PMID 33922500, 2021). "Knockdown of YBEY mRNA in breast cancer cell lines consistently decreased cell proliferation, colony formation, and migration/invasion, regardless of estrogen receptor status." (PMID 33922500, 2021). "We also show that k.d. of YBEY results in significant reductions in breast cancer cell proliferation, colony formation, migration, and invasion, in vitro." (PMID 33922500, 2021). "We performed in vitro functional assays using MCF-7, T47D, and MDA-MB-231 breast cancer cell lines and showed that knockdown of YBEY expression significantly inhibited proliferation, colony formation, and invasion/migration." (PMID 33922500, 2021). "Finally, we showed trends in YBEY expression patterns in breast tissues from The Cancer Genome Atlas (TCGA); early-stage breast cancers had elevated YBEY expression compared with normal tissue, but significantly decreased expression in late-stage disease." (PMID 33922500, 2021). "Of these, genes hypothesized to have a tumor-suppressor function included LINC00886, MAN2C1, SNUPN, and STC1, while YBEY, SEMA4A, and MUTYH may have an oncogenic role in breast carcinogenesis based on their associations with breast cancer risk." (PMID 32139696, 2020). "Our gene-based analysis indicated a potential oncogenic role of YBEY in breast cancer development." (PMID 32139696, 2020). "While higher YBEY expression appears to be beneficial in overall survival analyses, these data may be skewed due to the higher number of earlier stage breast cancers in TCGA or potentially confounded by estrogen receptor status, as observed in our survival analysis." (PMID 33922500, 2021). "Finally, we found that in the TCGA breast cancer (TCGA-BRCA) dataset, YBEY expression was significantly increased in tumors compared with normal tissues." (PMID 33922500, 2021).
acute pneumonia (1 paper, 2020). "Mutation of ybeY resulted in defective processing of the 16S rRNA, defective response to oxidative stresses, and attenuated virulence in the murine acute pneumonia model." (PMID 32605982, 2020). "To examine the role of YbeY in the virulence of P. aeruginosa, we utilized a murine acute pneumonia model." (PMID 32605982, 2020). "We find that the Pseudomonas aeruginosa endonuclease YbeY is required for rRNA processing and the bacterial virulence in a murine acute pneumonia model." (PMID 32605982, 2020). "YbeY is required for the virulence of P. aeruginosa in a murine acute pneumonia model." (PMID 32605982, 2020).
endometrioid carcinoma (1 paper, 2019). "C21ORF57 is a synonym for YBEY which according to COSM1031614, mutations in this gene in two TCGA samples have been associated with endometrioid carcinoma." (PMID 30620740, 2019).
metastatic disease (1 paper, 2021). "Data derived from TCGA provided evidence of differential YBEY expression depending on cancer stage, with metastatic disease having significantly lower expression compared with earlier stages." (PMID 33922500, 2021). "However, YBEY expression was significantly reduced in late-stage disease compared with early-stage, suggesting a potential molecular phenotype switch in metastatic disease compared with initial stages." (PMID 33922500, 2021).
infection (4 papers, 2014 to 2022). The state of being infected such as from the introduction of a foreign agent such as serum, vaccine, antigenic substance or organism. "Our in vitro infection assay revealed that the ybeY mutant was more susceptible to neutrophils." (PMID 32605982, 2020). "Taken together, these results suggest that YbeY plays a critical role during multiple stages of the V. cholerae's infection cycle." (PMID 24901994, 2014). "YbeY was originally discovered in S. meliloti as a stress regulator crucial to establish a chronic intracellular infection required for the nitrogen-fixing symbiosis within its host plant Medicago sativa." (PMID 24901994, 2014). "Comparing the gene expression profile between the ybeY mutant and the wild-type strain during infection might shed light on the roles of YbeY in the bacterial virulence." (PMID 32605982, 2020). "As V. cholerae is exposed to oxidative stress during host infection and UV radiation outside of the host, both stresses were tested as well, showing a consistent decrease in protection against oxidative and UV stress upon YbeY depletion." (PMID 24901994, 2014). "Lastly, intestinal colonization by the V. cholerae ybeY mutant is almost completely lost upon YbeY depletion in competition with the wild-type strain in infant mice, illustrating the overall reduced in vivo fitness or reduced ability to establish an infection." (PMID 24901994, 2014). "In Vibrio cholera, for example, the YbeY protein is a ribonuclease that is essential for virulence and stress regulation, whereas ribonuclease R is a virulence factor that is important during the first steps of infection, adhesion and invasion of eukaryotic cells by Campylobacter jejuni." (PMID 26694028, 2015).
tumor (3 papers, 2020 to 2023). "Further, we used data available in The Cancer Genome Atlas to explore trends in YBEY expression patterns in normal and tumor tissues." (PMID 33922500, 2021).
cancer (2 papers, 2019 to 2021). A tumor composed of atypical neoplastic, often pleomorphic cells that invade other tissues. "While YBEY k.d. may disrupt proper rRNA maturation and ribosomal biogenesis, migration and invasion of cancer cell lines depend on several factors, including chemokine/cytokine signaling, cytoskeletal rearrangements, and matrix metalloproteases." (PMID 33922500, 2021). "This evidence suggests that human YBEY may play a significant role in cancer pathogenesis." (PMID 33922500, 2021). "YBEY (C21orf57) is a highly conserved metalloprotein not-well characterized in cancer." (PMID 30808328, 2019).
mitochondrial disease (1 paper, 2020). "Involvement of ERAL1 in mitochondrial SSU biogenesis and the associated mitochondrial diseases were reported, and physical and genetic interactions between bacterial Era and YbeY were described." (PMID 32182356, 2020).
YBEY also shares sentences with these, for which no sentence is quoted: cholera (1 paper); fungal infection (1); type 2 diabetes (1).